AKT1 (AKT serine/threonine kinase 1)
Diseases named in the same sentence as AKT1 in open-access papers (continued):
Sharing a sentence is not in itself a finding about the gene and the disease.
prostate carcinoma (566 papers, 2003 to 2026). A carcinoma that arises from epithelial cells of the prostate gland. "Given the paucity of information, more studies are required to determine the mechanistic role of AKT1 in the progression and survival of prostate cancer, particularly considering the increased rate of AKT1 gene mutation in prostate cancer." (PMID 40214422, 2025). "AKT1, in particular, has been implicated in multiple biological processes in tumors, including prostate cancer." (PMID 38326539, 2024). "Analysis of genes linked to CpG sites in clusters 3–9, the less differentially methylated clusters, did identify some genes previously implicated in prostate cancer e.g., AKT1." (PMID 39661598, 2024). "In tumor metabolic studies, AKT1 activation was associated with the accumulation of aerobic glycolysis metabolites in prostate cancer." (PMID 38396845, 2024). "Functional enrichment analysis of AKT1 function shows its significant association with prostate cancer and various EMT-related proteins, genes and signaling pathways." (PMID 37759434, 2023). "This helps explain why a loss of miR-143-3p expression is detrimental in prostate cancer, since it can lead to increased AKT1 levels that subsequently promote EMT and tumor progression." (PMID 37759434, 2023). "This is the first study to show that miR-143-3p targets AKT1 in prostate cancer cells, and we propose that the loss of miR-143-3p is implicated in driving EMT." (PMID 37759434, 2023). "The EMT-linked gene AKT1 was subsequently shown to be a novel target of miR-143-3p in prostate cancer cells." (PMID 37759434, 2023). "Here, the authors show that resistance to allosteric inhibitors is mainly due to mutation of AKT1 while the ATP competitive resistance is driven by activation of PIM kinases in prostate cancer models." (PMID 35440108, 2022). "(2021) exhibited that Akt1- and Akt2-deficient prostate cancer CWR22rv1 cells exhibited an enormous invasive reduction in vitro and in vivo." (PMID 35508982, 2022). "For example, silencing of TRPM4, and in turn reduced Ca2+ influx in PC3 and LNCaP prostate cancer cell lines is associated with a decrease in basal AKT1 phosphorylation and reduced proliferation." (PMID 36230716, 2022). "Further, overexpression of AKT1 in prostate cancers upregulates CXCR4 expression and loss of PTEN in the cells enhances AKT-mediated expression of CXCL12 and CXCR4." (PMID 36012631, 2022). "Except for cancer cell autonormous Akt1, Akt1 deficiency in endothelial cells also facilitates prostate cancer metastasis due to activation of β-catenin." (PMID 34419139, 2021). "In prostate cancer Akt1 overexpression is associated with accumulation of glycolytic metabolites, whereas overexpression of MYC causes dysregulation in lipid metabolism." (PMID 33652667, 2021). "Chen and colleagues have also demonstrated a requirement for AKT in PTEN-deficient prostate cancer, as Akt1 haplodeficiency was found to suppress high-grade prostate intraepithelial neoplasia development within Pten heterozygous mice." (PMID 32630372, 2020). "Activating mutations in AKT1–3 are relatively rare in prostate cancer, while gene amplification has been observed in up to 4.5% (AKT1), 2% (AKT2), and 4.7% (AKT3) of prostate cancer cases, respectively." (PMID 33105713, 2020). "An alternative activating mechanism for this signaling pathway is the activating mutation in AKT1 itself, which has been found in human prostate cancer." (PMID 29671777, 2018). "In contrast, our own data revealed that overexpression of the activation-associated Akt1 mutants Akt1-E17K and Akt1-T308D/S473D accelerated DNA repair and promoted radiation resistance in murine prostate cancer cells and murine embryonic fibroblasts." (PMID 29562639, 2018). "To investigate the downstream mediator of enhanced transendothelial migration and lung colonisation by prostate cancer cells with the endothelial Akt1 loss, we determined the role of endothelial GSKβ-β-catenin pathway in this process." (PMID 29755115, 2018).
prostate carcinoma (continued). "Here we show that metastatic human PC3 and DU145 prostate cancer cells invade through Akt1-deficient human lung endothelial cell (HLEC) monolayer with higher efficiency compared to control HLEC." (PMID 29755115, 2018). "Both mutants accelerated the repair of DNA DSB in TrC1 prostate cancer cells with low level of endogenous Akt1 activity as well as in Akt1-deficient MEFs." (PMID 28209968, 2017). "Loss of this endopeptidase also leads to AKT1 (protein kinase B) activation, and contributes to the clinical progression of prostate cancer." (PMID 18827820, 2008). "EVs associated with prostate cancer have been found to contain AKT1." (PMID 40214422, 2025). "Interestingly, Patients 3 and 4, both with distant metastasis shared the same mutation in AKT1, a previously reported hot spot mutation in prostate cancer." (PMID 35880692, 2023). "We identified AKT1 as the most interesting candidate to investigate in more detail, since it appeared several times in our functional enrichment analyses as a gene linked to both prostate cancer and EMT." (PMID 37759434, 2023). "Additionally, an overview of the bidirectional network interactions of both molecules shows there are many other targets of miR-143-3p, several of which are linked to EMT and prostate cancer, plus many other miRNAs that are known to target AKT1." (PMID 37759434, 2023). "Instead, overexpression of Akt3 in a genetic model of PDGF-driven murine glioma or of the clinically relevant activating mutation Akt1-E17K in murine prostate cancer cells facilitated the repair of radiation-induced DNA damage, thereby increasing radiation resistance." (PMID 29562639, 2018). "Similarly, both PC3 and DU145 cells were able to transmigrate through ShAkt1 HLEC monolayer than a shControl HLEC monolayer, thus indicating that endothelial Akt1 loss augments prostate cancer cell transendothelial migration." (PMID 29755115, 2018). "Inducible shRNA knockdown of AKT1 or AKT2 in PTEN-deficient prostate cancer cells inhibited the formation of 3D spheroids, suggesting that both AKT isoforms may be required for initial tumour growth." (PMID 28082369, 2017). "In our MWA screening using 48 antibodies against proteins involved in Akt signaling and cell cycle regulation, we observed that triol caused reduction of Akt1, Akt2, cyclin E2, cyclin B1, phospho-c-Myc Thr58/Ser62, c-Myc, and phospho-Akt Ser473 in all three prostate cancer cell lines." (PMID 23785446, 2013). "We investigated whether the E17K substitution in AKT1 was associated with a specific growth pattern of prostate cancer and whether it corresponded with clinical outcome." (PMID 20407443, 2010). "The importance of each AKT isoform in PTEN-deficient prostate cancer remains unclear, with some preclinical data suggesting a higher dependency on AKT2 compared to AKT1, yet only deletion of Akt1 and not Akt2 has been shown to suppress prostate neoplasia in a Pten+/− transgenic mouse." (PMID 33105713, 2020). "Next, we determined whether pharmacological inhibition of β-catenin would inhibit enhanced transendothelial migration of human DU145 prostate cancer cells through Akt1-deficient HLEC monolayer in vitro and limit lung colonisation of murine RM1 prostate cancer cells in VECad-Cre-Akt1 mice in vivo." (PMID 29755115, 2018). "Therefore, we overexpressed either the respective single or the double phosphorylation-deficient mutants (Akt1-T308A, Akt1-S473A, or Akt1-T308A/S473A) in TRAMPC1 murine prostate cancer cells (TrC1) and measured the DSB repair kinetics and clonogenic cell survival upon irradiation." (PMID 30065170, 2018). "In the BPH-induced rat model, paeonol treatment similarly inhibited Akt1 expression levels in the prostate tissue, which is consistent with previous studies of paeonol in prostate cancer cell lines." (PMID 41011193, 2025). "Both AKT1 and AKT2 are required for PTEN-deficient prostate cancer spheroid formation but only AKT2 is essential for tumor spheroid maintenance." (PMID 41408399, 2025).
prostate carcinoma (continued). "Increased AKT1 activity has been observed in around 40% of breast and ovarian cancers and in over 50% of prostate cancers." (PMID 40943615, 2025). "In a related context, miR‐143‐3p was shown to inhibit EMT in prostate cancer by targeting AKT1 and to curb bone metastasis of Gleason 3+4 prostate cancer by targeting the LASP1‐mediated Wnt pathway." (PMID 40223182, 2025). "First, network pharmacology was used to predict the potential targets of Osthole, identifying 68 targets shared with prostate cancer, including AKT1, TNF, IL6, STAT3, and CTNNB1." (PMID 40978029, 2025). "As a mechanism, the authors demonstrated that AKT1 activation promotes migration of PC-3 prostate cancer cells via activation of integrin." (PMID 40214422, 2025). "KEGG pathway enrichment revealed that cancer-related pathways were widely enriched, with the Prostate cancer pathway ranking first, indicating that SR-CR AKT1, mTOR, and CASP9 were all enriched in the Prostate cancer pathway." (PMID 38326539, 2024). "Vascular endothelial growth factor-C protects prostate cancer cells from oxidative stress by the activation of mammalian target of rapamycin complex-2 and AKT-1." (PMID 37469162, 2024). "Using genetically engineered mouse models and tetracycline-regulated AKT isoform shRNA, it was found that in prostate cancer, AKT1 promotes tumor growth, and AKT2 promotes metastasis." (PMID 39614261, 2024). "Compared to control animals, Pb-Cre+PtenL/L mice developed a severe prostate cancer phenotype 9 weeks after birth, and IHC staining showed that the levels of S473 phosphorylation of AKT1 were increased in cancer tissues of Pb-Cre+PtenL/L mice." (PMID 38263319, 2024). "Some of the genes that have been linked to the development of prostate cancer are PIK3R1, SRC, STAT3, HSP90AA1, AKT1, MAPK1, SESR1, and AR." (PMID 39114070, 2024). "In contrast, phosphorylation at Ser264 was unchanged following the inhibition of AKT1 in the prostate cancer cell line PC-3." (PMID 38396845, 2024). "SR-CR inhibited the Prostate cancer signaling pathway by downregulating the expression of AKT1 and mTOR, and upregulating CASP9, leading to apoptosis in prostate cancer cells." (PMID 38326539, 2024). "The activation of AKT-1 is mediated by mTOR complex 2 (mTORC-2) within the tumor microenvironment, which protects prostate cancer cells from undergoing H2O2-induced cell death." (PMID 37469162, 2024). "In sum, our data indicate that PTEN alters AKT isoform dependency such that metastatic prostate cancer progression likely involves substrates preferred by AKT2 and/or AKT3, but not by AKT1." (PMID 37875657, 2024). "CXCL12 (SDF-1)/CXCR4 interactions play an essential role in prostate cancer migration and invasion to the bone by activating Akt1 and MMP-9 expressions." (PMID 36863017, 2023). "Contrarily, a constitutively-active Akt1 construct or the pharmacological JNK inhibitors attenuated SKI-178-induced cytotoxicity in prostate cancer cells." (PMID 37604912, 2023). "We showed that AKT1 expression is significantly upregulated in prostate cancer samples compared to normal prostate tissue and in tumors with a higher Gleason score, trends that are the inverse of the miR-143-3p expression profile in these samples." (PMID 37759434, 2023). "Our data suggest the miR-143-3p targeting of AKT1 exerts a similar regulatory effect in prostate cancer cells." (PMID 37759434, 2023). "This is the first report showing how downregulation of miR-143-3p can contribute to the development of prostate cancer through the targeting of AKT1." (PMID 37759434, 2023). "AKT is an important target and prognostic marker in prostate cancer and signification overexpression of AKT1, AKT2 and mTOR genes was observed in human prostate cancer samples compared with normal prostate gland tissue." (PMID 36936272, 2022). "Although previous studies have found that PI3K/AKT phosphorylates MED1 in prostate cancer cells, AKT1 and AKT2 are mainly localized outside of the nucleus." (PMID 35394046, 2022).
prostate carcinoma (continued). "In human prostate cancer, mutations and inactivation of Pten are more common than amplifications and activation of PIK3CA, PIK3CB, PIK3R1, and AKT1." (PMID 36358740, 2022). "As such, p27 deficiency abolishes this cellular senescence response and synergizes with Akt1 overexpression to induce invasive prostate cancer development." (PMID 36180910, 2022). "Although Akt is generally considered as oncogene, both Akt1 and Akt2 paradoxically inhibit prostate cancer cell migration by downregulating β1-integrin activity." (PMID 34419139, 2021). "Overexpression of AKT1 in prostate cancer cells was shown to upregulate the CXCR4 expression and, therefore, promotes intraosseous tumor growth as well as the formation of metastases with an osteolytic phenotype." (PMID 34064589, 2021). "In human specimens, we found Akt1 and Akt2 positively correlated, whereas Akt3 inversely correlated, with the overall survival of prostate cancer patients." (PMID 34591413, 2021). "The activation of CXCL12 chemokine has been reported to increase the motility of LNCaP and PC3 cells and induction of downstream pathways such as Akt-1 and metalloproteinases, which is involved in the regulation of prostate cancer cell migration." (PMID 33808801, 2021). "Out of 20 miRNAs experimentally validated to control the expression of AKT1 whose constitutional activation drives the emergence of the NEPC phenotype, several miRNAs were reported to be specifically implicated in prostate cancer." (PMID 34940756, 2021). "In this sense,a case-control study was performed that evaluated the possible relationship betweenpolymorphic variants of the genes PTEN, PI3K, AKT1, P504S (AMACR),and AR and prostate cancer susceptibility." (PMID 32484847, 2020). "Akt1 and Akt2 have also been shown to play opposite roles in regulating migration and invasion in breast cancer while they both inhibit prostate cancer cell migration and invasion." (PMID 31671832, 2019). "Modulation of AKT1 gene was noted in the transcriptomic data of PCAT-1 depleted prostate cancer cells." (PMID 30987615, 2019). "The analysis of large-scale genomic studies of the TCGA and other prostate cancer databases provided evidence that in the large majority of patients CHD1 loss and PTEN deletion (as well as AKT1, AKT2, AKT3, and PIK3CA gene alterations) were mutually exclusive." (PMID 31366128, 2019). "This study presents further evidence to show that TRPM4 regulates β‐catenin signaling and enhances the proliferation of prostate cancer cell lines, through a calcium‐dependent regulation of Akt1 and GSK‐3β activity." (PMID 28614631, 2018). "Nevertheless, this study demonstrates for the first time that Akt1 suppression in endothelial cells will promote prostate cancer metastasis involving β-catenin-mediated suppression of tight-junction proteins such as claudin-5, ZO-1 and ZO-2." (PMID 29755115, 2018). "Our results showed that NC treatment decreased expression of ERK1/2 and AKT1 proteins in prostate cancer cells and AKT1 and HSP27 cells in MCF-7 cells." (PMID 29444163, 2018). "In the current study, we investigated the effects of endothelial-specific knockdown of Akt1, a major endothelial isoform of Akt13 on prostate cancer cell invasion in vitro and metastasis in vivo using murine lung colonisation model of in vivo metastasis." (PMID 29755115, 2018). "We determined how endothelial deletion of Akt1 promotes prostate cancer cell invasion in vitro and metastasis to the lungs in vivo in endothelial-specific Akt1 knockdown mice." (PMID 29755115, 2018). "Altogether, these results demonstrate the endothelial cell-specific role of Akt1 in prostate cancer metastasis." (PMID 29755115, 2018). "In PC3 prostate cancer cells, down-regulation of AKT1 induces activation of β1-integrins and promotes cell adhesion, migration and invasion." (PMID 28765579, 2017).
prostate carcinoma (continued). "AKT1 activation has been reported in gastric, prostate cancer and somatic mutation in pleckstrin homology domain (PHD) of AKT1 was reported in human breast, colorectal and ovarian cancers." (PMID 28881811, 2017). "We thank Dr. Irwin H. Gelman from Roswell Park Cancer Institute (Buffalo, New York, USA) for LNCaP prostate cancer cell lines infected with Decode RNAi viral libraries and myr-Akt1 plasmid." (PMID 27966458, 2017). "In prostate cancer patients, phosphorylated Akt1 is more highly expressed at the membrane of high grade, poorly differentiated tumours." (PMID 27661110, 2016). "In pursuit of this goal, we have so far shown that Akt1, predominant Akt isoform in prostate cancer cells is integral for tumor growth and invasion." (PMID 25714023, 2015). "High level of phosphorylated AKT1 is a strong predictor for prostate cancer recurrence while AKT2 is essential for survival of PTEN-deficient prostate tumors." (PMID 26318033, 2015). "A recent siRNA screen identified AKT1 as a target that impaired the growth of AR + prostate cancer cell lines, consistent with the PI3K pathway playing an essential role in survival of AR-dependent cells." (PMID 25103565, 2014). "In particular, both AKT1 and 2 seem to play an inhibitory role in prostate cancer cell migration and invasion." (PMID 23165443, 2013). "As a result of the reported roles of Akt1 in prostate cancer tumorigenesis, the PI3K/AKT pathway is being closely examined as a therapeutic target." (PMID 22509301, 2012). "AKT1 activity is frequently elevated in breast and prostate cancers while AKT2 has been shown to be upregulated in pancreatic and ovarian carcinomas." (PMID 21869924, 2011). "Apoptotic activity of Par-4 is reduced when bound and phosphorylated by AKT1 in prostate cancer cell lines." (PMID 20433755, 2010). "In this study, we analysed the prevalence of AKT1(E17K) in a larger cohort of prostate cancer patients." (PMID 20407443, 2010). "The OncoMap platform identified rare AKT1 mutations in these tumor types, as well as single AKT1E17K instances in endometrial, esophageal squamous, gastric, and prostate cancers." (PMID 19924296, 2009). "We investigated the correlation between the expression and localisation of Akt-1, Akt-2, Akt-3, phospho-Akt proteins and the clinicopathological parameters in 63 prostate cancer specimens." (PMID 16721361, 2006). "This is the first report demonstrating in patients with prostate cancer and the particular role of Akt-1 isoform expression as a prognostic marker depending of its localisation." (PMID 16721361, 2006). "In total, 373 prostate cancer tissues from 63 cancer prostate patients spotted on tissue microarrays were evaluated for Akt-1, -2, -3 expressions by IHC using isoform-specific antibodies." (PMID 16721361, 2006). "In fact, the specific expression and role of Akt-1, -2 and -3 in prostate cancer tissues is still scant." (PMID 16721361, 2006). "To further explore the role of ME2fl phosphorylation by AKT1 in tumorigenesis in vivo, we used age-matched and genetic background-matched Pb-Cre-PtenL/L mice as controls to monitor tumor development in the Pb-Cre+PtenL/L prostate cancer model." (PMID 38263319, 2024). "In summary, this is the first study to report that miR-143-3p overexpression in prostate cancer may inhibit EMT by targeting AKT1." (PMID 37759434, 2023). "Finally, double KO of Akt1 and Akt2 genes potently decreased prostate cancer cell metastasis in vitro and in vivo." (PMID 35508982, 2022). "It has also been shown that MST1 may directly interact with and inhibit the AKT1 serine/threonine kinase in human prostate cancer cells." (PMID 35954292, 2022). "Polymorphic variants in the PTEN (rs2735343),PI3K (rs2699887), AKT1 (rs2494750),AR (rs17302090), and AMACR (rs3195676)genes were evaluated as possible molecular markers of susceptibility, prognosis,and progression of prostate cancer (PCa), in a case-control study." (PMID 32484847, 2020).